MYD88 (MYD88 innate immune signal transduction adaptor)
Diseases named in the same sentence as MYD88 in open-access papers (continued):
Sharing a sentence is not in itself a finding about the gene and the disease.
cancer (continued). "TLR signaling pathways were abundantly accumulated in Mac_C2, such as MyD88 deficiency (TLR2/4), IRAK4 deficiency (TLR2/4), regulation of TLR by endogenous ligand, and disease associated with the TLR signaling cascade, which were related to the inflammatory mechanisms of in cancers." (PMID 38918785, 2024). "However, polymerizing inhibitors that directly target MyD88 may have more precise anti-inflammatory and anti-cancer effects." (PMID 38785969, 2024). "However, the molecular mechanism of MYD88-induced cancer development is poorly understood." (PMID 33597599, 2021). "However, TLR, TRIF, and MyD88 expressions were similar in both cancer tissues." (PMID 34306609, 2021). "Although we observed almost identical TLR expression patterns in these carcinoma tissues, the contribution of TLRs to the MyD88-dependent pathway in PTC and ATC remains unclear, and more complicated mechanisms may occur following TLR signaling and activation of the MyD88-dependent pathway." (PMID 34306609, 2021). "The role of MyD88 in cancer prognosis might differ in different cancers." (PMID 32477927, 2020). "Additionally, the activation of TLR4/MyD88 results in Sp1 accumulation in cancer progression." (PMID 32144747, 2020). "The characterisation of specific MyD88 pathways driving cancer- and chemotherapy-induced cognitive dysfunction will be important, and may point to additional genetic polymorphisms or biomarkers of these pathways useful for identifying patients at high risk of cognitive dysfunction." (PMID 26332828, 2015). "However, the association between TLR4/MyD88 signalling and cancer mortality has not been well investigated in clinical samples." (PMID 22533866, 2012). "The mechanistic pathway linking F. nucleatum to cancer involves adhesion to epithelial cells, followed by internalization and activation of TLR4/MYD88 signaling." (PMID 40869140, 2025). "We observed that MyD88, p-ERK, p-NF-kB, TNF-α, IL-1β, and IL-6 were significantly suppressed in cancer cells treated with SsnB compared to the control groups." (PMID 40143078, 2025). "Mechanistically, we found that miR-3124-5p secreted by CAFs exerts a pro-cancer effect by inhibiting TOLLIP expression and promoting the TLR4/MyD88/NF-κB signaling pathway." (PMID 39735680, 2025). "Assessing the influence of MyD88 on the TIME, our study encompassed an appraisal of the efficacy of cancer immune responses, an examination of immune cell infiltration, and a dissection of the expression profiles of immune checkpoint genes." (PMID 39744584, 2025). "Additionally, recent studies demonstrate that both natural and synthetic inhibitors targeting MYD88 can effectively disrupt NF-κB signaling and exhibit anti-inflammatory and anti-cancer effects, which could indicate the importance of understanding its role in the progression of CLL to RS." (PMID 39596634, 2024). "On the other side, cancer colonocytes activated the expression of proinflammatory TLR4 and IL1R1 receptors, while reducing MYD88 in cells treated with the mixture of bacteria and hPA120." (PMID 36296918, 2022). "TLRs are key molecules involved in inflammation‐driven cancer and all of them, except TLR3, commonly use MYD88 as the downstream adapter protein leading to activation of NF‐κB signalling." (PMID 36433652, 2022). "Inflammatory IL-1β (MyD88) and NF-κβ signaling pathways were upregulated in SED + T compared to all other groups indicating inflammatory pathways likely play a role in the cancer-mediated cardiac dysfunction." (PMID 36531941, 2022).
cancer (continued). "In cancer colonocytes, the expression of TLR4 and IL1R increased after BM + hPA120 treatment, whereas the secretion of IL-8 and MYD88 and TNFR expression decreased (p < 0.01)." (PMID 36296918, 2022). "We found that periodontal pathogens promote cancer aggressivity via crosstalk between integrin/FAK and TLR/MyD88 signaling pathways that is reversible by bacteriocin/nisin treatment." (PMID 33002094, 2020). "TLR9 promotes survivability of cancer cells by activating the TLR9—MyD88 –NF-kB signaling pathway, whereas AIM2 induces apoptosis in cancer cells being a part of the inflammasome." (PMID 31205871, 2019). "On the other hand, the inhibition of TLR4 limited cancer progression, while the inhibition of the TLR adapter protein myeloid differentiation primary response gene 88 (MyD88) unpredictably worsened pancreatic inflammation and cancer development." (PMID 29563853, 2018). "It was reported in many studies that miR-940 was highly expressed in normal tissues compared with tumors, and miR-940 was shown to inhibit the migratory and invasive potential of cancer cells by suppressing CXCR2, MIEN1, MyD88, Nestin, and ZNF24." (PMID 28423620, 2017). "Among these eleven putative genes, including genes such as MYD88, FGFR2 and THBS1, stimulative or suppressive effects on cancers have been shown by the experiments." (PMID 28384236, 2017). "The previous studies reported roles of MyD88 and/or IRAK adapter proteins in the innate immunity, inflammation and cancer metastasis." (PMID 26312071, 2015). "Subsequent analysis focused on pan‐cancer studies of the two core prognostic genes, CD36 and MYD88." (PMID 38742843, 2024). "The fact that Rag1-/-, Batf3-/- or Myd88-/- mice did not display VitD-driven increased immune resistance to cancer was not because immune defects in those mice compromised the ability of VitD3 high diet to promote the favorable alterations in microbiota." (PMID 38662827, 2024). "A preclinical study using a xenograft animal model showed that F. nucleatum activates autophagy of cancer cells through toll-like receptor (TLR)-4 and myeloid differentiation primary response 88 (MYD88) signaling pathway, potentiating CRC resistance to oxaliplatin and 5-fluorouracil (5-Fu) regimens." (PMID 35914737, 2023). "MYD88, a myeloid differentiation primary response protein, was determined to correlate with OS and PFI, suggesting a potential prognostic value in various types of cancer." (PMID 37456890, 2023). "As an important anti-inflammatory protein in the MyD88 pathway, targeting of IRAK-M is a potential way of boosting the immune system in patients with bacterial infection, immunoparalysis or cancer, since IRAK-M targeting in animal models of these diseases improves outcome." (PMID 38268724, 2023). "Importantly, LPS sensitizes the therapeutic response of both TNBC and ER+ BC to IAP antagonist therapy by inducing the cancer cell apoptosis through toll-like receptor 4 (TLR4) and MyD88 stimulated TNFα production." (PMID 36119107, 2022). "Although inhibition of MyD88 signaling in MDSCs is proving to be a promising treatment for cancer, effective administration of these agents has not yet been accomplished." (PMID 35089465, 2022). "In colitis-associated cancer (CAC) models, mice with Col6a1+ fibroblast-specific deletion of Stat3 or Ikbkb (but not Tlr4 or Myd88) demonstrate reduced cancer development." (PMID 36591258, 2022). "The cancer colonocytes responded to the presence of the mixture of fecal bacteria and hPA120 (V BM + hPA120 and O BM + hPA120 samples) by an increase of IL1R1 and a decrease of MYD88 expression compared to CTRL and/or hPA120 controls." (PMID 36296918, 2022). "Furthermore, the key genes correlated with KMO, such as the MYD88, IRF1, IL-18, and CASP1 genes, manipulate the inflammation where many cancers arise." (PMID 34683090, 2021).
cancer (continued). "Therefore, to investigate the mechanism of inflammation-induced TIC generation and treatment of cancer induced by chronic inflammation, it is important to determine the molecular mechanism of HIF-1α induction in response to MYD88 signals in more detail." (PMID 33597599, 2021). "Interestingly, alterations in JAK2, MYD88 and NPM1 genes, already have drugs FDA approved for other cancers." (PMID 33668731, 2021). "Finally, other signaling typically involved in both SSc and cancer development are TGF-beta receptor and MyD88/Toll-like receptors pathways." (PMID 30866419, 2019). "Stimulation with IFN-γ, TLR ligands and LPS via MyD88, TRAF6, MEK, STAT1, NF-κB and PI3K-dependent pathways increased PD-L1 expression in different types of cells, such as inflammatory cells, fibroblasts and cancer cells." (PMID 29690901, 2018). "Although the role of MYD88 in WM was initially reported in 2012, it was not until 2016 that MYD88 testing was included in the National Cancer Care Network (NCCN) Guidelines." (PMID 28286680, 2017). "Previously, our lab described the development of a synthetic ligand-inducible MyD88/CD40 (“MC”) fusion protein, comprising signaling elements from MyD88 and CD40, two FKBP12-based ligand-binding domains, and a myristoylation membrane localization domain, as an adjuvant for cancer vaccines." (PMID 27741278, 2016). "Therefore, effects of chemotherapeutics on cancer spheroid formation were compared between MyD88-positive EOC cells (R182) and MyD88-deificient EOC cells (A2780)." (PMID 27708225, 2016). "We identified Toll-like receptor 1 (TLR1), TLR2, TLR4 and TLR8 gene expression levels and downstream gene, i.e., interleukin-6 (IL-6), IL-8, interferon-α (IFN-α) and myeloid differentiation primary-response protein-88 (MyD88), expression levels in CRC patients and in cancer cell lines." (PMID 25547486, 2014). "The average expression of miR-21 and miR-146a in MyD88 negative cancers was increased relative to the average of the MyD88 positive group (p<0.001)." (PMID 24977712, 2014). "MiR-21 and miR-146a expression was significantly increased in MyD88 negative cancers (p<0.05), indicating their participation in regulation." (PMID 24977712, 2014). "The associated levels of TLR4 & MyD88 mRNA were statistically unaltered between the MyD88 positive and negative cancers (p = 0.8777 and 0.1348, respectively)." (PMID 24977712, 2014). "The possible apoptotic pathways for anti-cancer effects of curcumin on cell signal transduction include PI3K, Akt, mTOR, ERK5, AP-1, TGF-β, Wnt, β-catenin, Shh, PAK1, Rac1, STAT3, PPARγ, EBPα, NLRP3 inflammasome, p38MAPK, Nrf2, Notch-1, AMPK, TLR-4, and MyD-88." (PMID 41149437, 2025). "In addition, classical and non-classical MyD88 inhibitors were collated to provide insights into potential cancer treatment strategies." (PMID 38785969, 2024). "In addition to F. nucleatum, several other oral bacteria, such as Treponema denticola, could promote cancer aggressivity via crosstalk between the integrin/FAK and TLR/MyD88 signaling pathways." (PMID 38589501, 2024). "Thus it is likely that MyD88 signalling is also key to cognitive dysfunction in cancer pain patients, but to our knowledge this has not been specifically investigated to date." (PMID 26332828, 2015). "Most TLRs signal via the myeloid differentiation primary response gene 88 (MyD88) and are expressed in both lymphoid and non-lymphoid tissues (predominantly in the former), with increasing evidence that they play important roles in cancer pathogenesis." (PMID 24977712, 2014). "Nevertheless, the facts that TLR9 agonists increases IgM secretion from cancer cells and that this increase can be abolished by chloroquine and MyD88 knockdown with siRNA suggest that the expression and secretion of cancer-derived IgM is mediated through the TLR9-MyD88 pathway." (PMID 23251529, 2012).
cancer (continued). "Although our experiment using mouse cells might not reflect all the processes of human inflammation-induced cancer, the identification of the basic regulatory mechanism of the MYD88-NF-κB-HIF-1α activation pathway and its involvement in TIC production is important." (PMID 33597599, 2021). "Thus, the TIR domains from MyD88 and TRIF, in addition to interacting with Ras, might be essential to the Ras-mediated signaling cascade and inflammatory responses in immune cells such as macrophages and even cancer cells." (PMID 32422978, 2020). "However, carcinoma samples with MMP-11 positive MICs showed a more important increase in the mRNA level of 19 factors: IL-1, −5, −6, −8, −17 and −18, ADAM-8, −10, −15, and −23, ADAMTS-1, −2, and −15, IFNβ, MMP-1, as well as mediators related to inflammation (CCL-3, IRAK-4, MyD88 and NFκB)." (PMID 23145063, 2012). "In agreement with our previous observations in human cancer tissues, MyD88-positive EOC R182 cells showed relatively enhanced levels of NAG-1 protein, compared with the levels of NAG-1 in MyD88-negative A2780 cells." (PMID 27708225, 2016). "The enhanced phosphorylation of NFκB in CRC cells after palmitic acid treatment suggests that the activation of the TLR4 signaling pathway is, at least in part, due to the enhanced TLR4, MyD88, and TIRAP expressions in the cancer cells but not a direct binding of palmitic acid to the TLR4 protein." (PMID 34385421, 2021).
bacterial infection (115 papers, 2009 to 2025). "MyD88 plays a key role in the innate immune defense against pathogens, and it has been reported that autosomal recessive MyD88 deficiency in children is associated with increased susceptibility to pyogenic bacterial infection." (PMID 38946731, 2024). "Patients with autosomal recessive MyD88 deficiency otherwise healthy, present with life-threatening, often recurrent pyogenic bacterial infections, including invasive pneumococcal disease." (PMID 36756122, 2023). "Humans with genetic defects in the central TLR/IL-1R signaling adaptors MyD88- or IRAK-4 have increased susceptibility to pyogenic bacterial infections, but only during infancy and early childhood." (PMID 31214180, 2019). "While the impact of TLR8 in bacterial infections in vivo still is unclear, we find these new data interesting in the context of human MyD88- and IRAK-4 deficiency, where signaling by most TLRs and IL-1Rs is lost." (PMID 31214180, 2019). "There was also a moderate positive correlation between the expression Myd88-Tnfrsf11 and Tlr2-Myd88, suggesting the relevance of Tlr2-Myd88 in bone loss due to bacterial infection." (PMID 29995146, 2018). "Although L93P and R196C occur in the two different domains of MyD88, one in the DD and the other in the TIR domain, they both cause autosomal recessive MyD88 deficiency that results in life-threatening, recurrent pyogenic bacterial infections." (PMID 30583727, 2018). "Children with genetic deficiency in MyD88, an essential adaptor for all TLRs but TLR3, or IRAK4, a kinase downstream of MyD88, have an approximately 50% risk of dying from invasive bacterial infections in the first 8 years of life." (PMID 29209311, 2017). "In one such study, children carrying rare SNPs within MyD88 (in-frame MyD88 deletion or missense mutations Leu93Pro Arg196Cys) suffered from very severe pyogenic bacterial infections." (PMID 23730203, 2012). "Taken together, these results suggest that OTUD4 negatively regulates K63-linked ubiquitination of MyD88 and MyD88-dependent activation of NF-κB and MAPKs, thereby restricting the expression of AMPs in IECs and promoting bacterial infection and inflammation in the gut." (PMID 37193092, 2023). "Besides, a similar improvement with age has been reported in children with impairment of TLR signaling (IRAK-4 and Myd88 deficiencies), in whom bacterial infections become rarer with age." (PMID 32457756, 2020). "Myd88-/- mice have enhanced susceptibility to, and morbidity from, bacterial infection." (PMID 30978245, 2019). "Our findings that MyD88 and IL-1R mediate antibacterial protection in bone are consistent with data from previous studies demonstrating that Myd88-/- and Il1r1-/- mice have enhanced susceptibility to bacterial infection in various experimental models." (PMID 30978245, 2019). "Although this study does not fully evaluate the molecular mechanisms of bone resorption during the periapical lesion, we hypothesize that these results demonstrate the relevance of TLR2 and MyD88 in bone loss from bacterial infection." (PMID 29995146, 2018). "Although it is known that MyD88-deficient mice are highly susceptible to a wide range of bacterial infections, the cell type-specific contribution of MyD88 in protecting the host against intestinal bacterial infection is only poorly understood." (PMID 28520792, 2017). "The observation that MyD88 deficient mice have impaired monopoiesis during bacterial infection does however suggest that there may be a hematological anomaly that warrants further investigation." (PMID 29259211, 2017). "It has been shown that mouse MyD88 deficiency leads to susceptibility to infections of various pathogens and human MyD88 deficiency occasionally exposes patients to life-threatening pyogenic bacterial infections." (PMID 25415419, 2014).